TNF (tumor necrosis factor)
Diseases named in the same sentence as TNF in open-access papers (continued):
Sharing a sentence is not in itself a finding about the gene and the disease.
tumor (continued). "Analysis at later time points could not be performed because of complete tumor regression in most of the TNF-deficient mice." (PMID 29273790, 2017). "Indeed, macrophages can release apoptosis-inducing soluble factors, such as nitric oxide (NO) and TNFα, exert phagocytosis based on the expression of signal molecules on the surface of tumours cells, such as phosphatidylserine and calreticulin, and clear viable antibody-coated tumour cells." (PMID 28404796, 2017). "However, in the presence of HER2(+) NCI-N87 tumor target, antitumor TH1 cytokines (TNFα and IFNγ) were released but only in the presence of BsAb, a format previously shown to induce immunologic synapse formation between the T cells and tumor targets." (PMID 28405494, 2017). "These cells function to stabilize tumor vasculature by infiltrating tumor masses and differentiating into tumor-associated macrophages, which then release a multitude of angiogenic factors and cytokines, such as vascular endothelial growth factor (VEGF), TNF-α, and matrix metalloproteinase-9." (PMID 28239396, 2017). "Moreover, the expression level of TNF-α increased with tumor progression." (PMID 29299026, 2017). "Interestingly, whereas a single anti-PD-1 injection failed to promote tumor rejection in WT mice, it triggered total rejection of more than 30% of tumors in TNF-deficient mice." (PMID 29273790, 2017). "Thus, in contrast to tumor cell-derived TNF-α, immune cell- derived TNF-α may exert protective effects, or at least indicate protective antitumor immune responses." (PMID 29069789, 2017). "Circulating lymphocytes can secrete several cytokines, such as IFN-γ and TNF-α, to control tumor growth and improve prognosis of cancer patients, and the decreased lymphocyte count and function cannot be responsible for immune surveillance to remove tumor cells." (PMID 29029493, 2017). "Additionally, our data demonstrated that AG could sensitize tumor cells to TNFα-triggered cell death via inhibiting the activity of NF-кB." (PMID 28199969, 2017). "Moreover, P. americana extracts markedly inhibited tumor growth without causing toxicity of immune organs in S180 tumor-bearing mice, which may be related to an increase in TNF-α in the serum of tumor-bearing mice." (PMID 28919922, 2017). "Moreover, there was a significant increase in immune organs index, lymphocyte proliferation, NK cell cytotoxic activity and serum TNF-α level, suggesting that hemocyanin could improve the immunity of the S180 tumor-bearing mice." (PMID 28854214, 2017). "It will be intriguing to determine whether targeting of TNFα to the tumor, or otherwise stimulating TNFR signaling at this site, may encourage differentiation of tumor vessels toward an HEV-like phenotype, and whether this will in turn enhance T cell infiltration further, and/or antitumor responses." (PMID 29312327, 2017). "Global increase of hepatic interleukin-1β, interleukin-6, tumor necrosis factor-α and hepatocyte growth factor was detected in low-fat/high-carbohydrate and high-fat with respect to standard diet fed mice as well as in tumor with respect to non-tumor bearing mice." (PMID 28881825, 2017). "Additionally, from the tumor-associated factors analyzed (VEGF, RANK-L, TNF-alpha and HIF-1alpha) that could be putatively associated to the impaired glucose/insulin metabolism, only VEGF was found overtly elevated in BCa patients compared to controls." (PMID 29113405, 2017). "The development of TNF inhibitors was an important advance in the treatment of these diseases, although their use remains controversial in patients with a history of cancer because of the possible effect of this cytokine on carcinogenesis and tumor progression." (PMID 28717771, 2017). "In addition to proinflammatory factors (e.g., TNF-α), our results indicate that exosomes from tumor cells may also serve to activate Notch signaling in the skeletal muscle." (PMID 27378829, 2016).
tumor (continued). "On the other hand, local effects of endogenous TNF, released from tumor cells and from tumor microenvironment, may be local and long-lasting and they could be mediated by both TNF receptors, with TNF–TNFRII axis having a distinct role because it requires tmTNF and cell-to-cell contacts." (PMID 27148266, 2016). "Thus, we hypothesized that prolonged in vivo blockade of TNF with pharmacological agents may result in anti-tumor effects." (PMID 27148266, 2016). "TNFα also induces cytotoxic activity in macrophages, and so mast cell-derived TNFα may play a pivotal role in the cytokine pathways influencing cytotoxic T cells and macrophages within the tumour islets, and thus have important consequences on cytotoxicity against tumour cells." (PMID 27922077, 2016). "Moreover, wogonoside inhibited the mRNA levels of IL-1β, IL-6 and TNF-α in tumor tissues." (PMID 27102438, 2016). "Furthermore, TNF blockade strongly diminished tumor development in AOM/DSS-treated mice." (PMID 27148488, 2016). "However, TNF-α preactivated AD-MSCs significantly inhibited tumor growth, metastasis and improved survival rate in tumor bearing mice and this antitumor effects were remarkably intensified by single dose irradiation one day prior to initial administration of cells." (PMID 27329316, 2016). "Moreover, overexpression of cytokines such as tumor necrosis factor α (TNFα), a cytokine involved in several signaling pathways and in inflammation, could lead to increased tumor formation in nude mice." (PMID 27270649, 2016). "Since IFN-γ and TNF exert synergic cytotoxic effects on endothelial and tumor cells, the presence of these Th1-type cytokines in the liver microenvironment, the tumor site, could significantly contribute to the antitumor effects promoted by oral Salmonella-based immunotherapy." (PMID 26973649, 2016). "Another reason for the increase in Hsp70 in tumor cells is the need for homeostatic mechanisms based on the chaperone, which confer efficient tolerance to the effects of chemical and biological stressors such as reactive oxygen species or tumor necrosis factor." (PMID 26959111, 2016). "On the other hand as TNFα and IL-6 signaling have been also shown to be involved in HCC oncogenesis, the observed anti-inflammatory effects of IGF-I encoding vectors might oppose tumor development in the cirrhotic liver." (PMID 27658043, 2016). "Therefore, we suggest that TNF-α may have circulated from the tumor to skeletal muscle and interfered with muscle stem cell activity and muscle regeneration via interaction with Notch signaling." (PMID 27378829, 2016). "Also, high plasma levels of TNFα correlate with higher tumor stage." (PMID 26918940, 2016). "Furthermore, a tumor-specific TNF production by IHIC was found in immunized mice." (PMID 26973649, 2016). "NK cells induce the tumor cell apoptosis by 1) secretion of cytoplasmic granules, perforin and granzymes, 2) expression of death receptor-mediated apoptosis or 3) secretion of TNF-α and destroying tumor cells through antibody dependent cellular cytotoxicity by expressing CD16." (PMID 27686848, 2016). "Thus, secretion of TNF-α either induced by LPS or endogenous ligands could promote the fusion of tumor cells and other cells." (PMID 27187369, 2016). "However, dysregulated TNF-α signaling can also promote tumor formation and growth." (PMID 28536374, 2016). "Furthermore, TNF-α and IL-1β are important for the tumor suppressive effects of S. enterica." (PMID 27835896, 2016). "IL-17 was the signature cytokine of Th17; researches showed that IL-17 could enhance the cytotoxic effects of NK cells against tumor cells by augmenting the expression of cytotoxic molecules including tumor necrosis factor-α (TNF-α), interferon-γ (IFN-γ), Perforin, and Granzyme B." (PMID 27722177, 2016). "Therefore, the use of TNF-expressing tumor cells for drug delivery shows potential." (PMID 27548121, 2016). "Thus, our study uncovers anti-tumor effects of systemic TNF ablation in vivo." (PMID 27148266, 2016).
tumor (continued). "Furthermore, low-dose TCP-1/TNFα (1 ng/mouse) potentiated the antitumor effect of 5-fluorouracil (5-FU) by normalizing the tumor vasculature, facilitating the infiltration of immune cells to the tumor as well as improving 5-FU penetration into the tumor mass." (PMID 27342639, 2016). "However, in the LSPS-treated groups, the production of TNF-α and IL-2 was enhanced, indicating that LSPS administration could improve immune function in H22 tumor-bearing mice by promoting TNF-α and IL-2 production." (PMID 27827862, 2016). "Furthermore, the tumor specimen expressed tumor necrosis factor-α (TNF-α)." (PMID 26951080, 2016). "In addition, the pattern and intensity of the immune response against the tumor or the responsiveness of the tumor cells to innate immune responses (such as sensitivity to TNF-α or antiviral responses) may be contributing factors." (PMID 27806313, 2016). "Tumor metastasis comprises different processes that lead tumor cells move away from the tumor to a distant location and some authors suggested that stromal cells regulate the production of various factors implicated in metastasis process such as COX2, TNF-α, IL-6, and IL-11." (PMID 27195300, 2016). "NF-κB-activated TNFα then induces tumor cell death in an autocrine mechanism, whereas increased Fas in the tumor cells may increase tumor cell sensitivity to FasL-mediated cytotoxicity of tumor-reactive CTLs in the tumor microenvironment." (PMID 27014915, 2016). "Hence, our data suggests that downregulation of TNF-α, IL-6 and IL-8 cytokines could account, at least partly, for the inhibition of tumor growth and metastasis mediated by Rhus coriaria." (PMID 26888313, 2016). "In contrast, macrophages that phagocytose tumor cells undergoing secondary necrosis, which release danger-associated molecular patterns (DAMPs) such as HMGB1, are M1-activated, lead to increased secretion of inflammatory cytokines (TNFα, IL-1β, and IL-12), and promote Th1 responses." (PMID 26997761, 2016). "Additionally, tumor-cell-derived TNF-α directly accelerates MMP-9 expression in fibroblasts." (PMID 25767513, 2015). "It is evident that inflammatory cytokines and chemokines, for example, tumor necrosis factor-alpha (TNF-α), IL-1 and IL-6, and interferon gamma (IFN-γ), which can be produced by the tumor cells and/or tumor-associated leukocytes and platelets, may add directly to the development of malignancy." (PMID 25814785, 2015). "Notably, ectopic overexpression of Cystatin A rescued tumor cells from TNF-induced apoptosis." (PMID 25648368, 2015). "However, there is also evidence that, under certain conditions, TNFα can act as a tumor promoter." (PMID 25663851, 2015). "Thus, TNF-α has the potential to promote tumor cell extravasation." (PMID 26631692, 2015). "We found that HIFU treatment decreased circulating B16F10 cells and pulmonary metastasis nodules while increased IFN-γ and TNF-α in the peripheral blood and cumulative mouse survival, which was associated with inhibition of miR-134 expression and activation of CD86 expression in tumor tissues." (PMID 26485753, 2015). "Besides the MAPK pathway, TNFα-Tpl2 mediated pathways could be additional therapeutic targets for developing anti-tumor agents since TNFα-mediated COX2 expression plays an important role in inflammation and carcinogenesis." (PMID 25723737, 2015). "For example, the overexpression of Cystatins, combined with normal expression levels of cysteine protease inhibitor in tumor cells, may augment the metastatic potential of a cancer via protection of the tumor cells against tumor necrosis factor (TNF)-mediated apoptosis." (PMID 25648368, 2015). "Malignant cells may also produce TNF-α, which may enhance tumor development." (PMID 26220864, 2015).
tumor (continued). "In the intestine, subsets of ILC1 are also cytokine producers (IFN-γ and TNF-α) after in vitro stimulation with IL-12 + IL-15 or IL-12+ IL-18 or after mucosal infection.They can also also degranulate after in vitro stimulation in the presence of tumor cell line." (PMID 26630176, 2015). "The tumor immunogenicity could also be shut by high levels of immune suppressive cytokines including transforming growth factor-β (TGFβ), tumor necrosis factor-α (TNFα), and IL10, in the tumor microenvironment." (PMID 26579545, 2015). "Furthermore, three of the prognostic cytokines/chemokines, CXCL9, IL-5, and TNF, when expressed at an increased level in specific tissue or cellular environment, may confer a downregulatory effect on tumor growth." (PMID 25825910, 2015). "In conclusion, the Nidus Vespae decoction could promote the proliferation of human PBMC, enhance the tumor cell-killing activity of CTL, elevate the IgG production of B cells, and strengthen the tumor cell phagocytosis as well as the cytokines (TNF-α and IL-6) production of monocytes." (PMID 26339270, 2015). "Moreover, we previously showed that curcumin can inhibit the IDO expression induced by IFN-γ and the EMT induced by TNF-α, suggesting curcumin could be a useful agent for antitumor therapy when combined with tumor vaccines." (PMID 26305550, 2015). "Indeed, phase I/II trials in RCC demonstrated an anti-tumor effect of anti-TNFα treatment." (PMID 26447542, 2015). "Furthermore, studies have proposed that systemic TNF-α might also be involved in the early development of some tumours." (PMID 26508818, 2015). "In contrast, rejection is associated with massive infiltration of the tumor bed by leukocytes, predominantly ED1+ microglia/macrophages, CD4+ T helper cells and CD8+ effector cells, and correlates with elevated serum levels of pro-inflammatory cytokines IL-1β, IL-18 and TNF-α." (PMID 26291724, 2015). "Thus, IL-4 and TNFα, which could be released by immune cells of the tumor microenvironment, are able to control the B7-H1 expression in RCC thereby altering T cell responses." (PMID 24885059, 2014). "In addition, TNF-α production by macrophages activates the Wnt/β-catenin pathway, which is also associated with tumor development by a non-resulting anti-inflammatory response." (PMID 24829560, 2014). "Interestingly, both the side-effects and reduced anti-tumor effects of NF-κB inhibitors in vivo might be due to the excessive sensitivity of NF-κB-inactivated cells to TNF-induced activation of JNK signaling." (PMID 25526629, 2014). "In summary, the findings in this study not only highlight the reversibility of neutrophil function in tumor-bearing state, but also suggest that neutrophil priming by IFN-γ/TNF-α might be a potential approach to eliminate residual tumor cells in comprehensive strategy for tumor therapy." (PMID 25587026, 2014). "Third, SAA may enhance tumor cell invasion and metastatic spread by becoming directly involved in enhancing the activity of matrix degrading enzymes (MMP/TIMP-1) and by increasing TNFα production in and through its association with collagen cleavage in vivo." (PMID 24447576, 2014). "Here, eight hours following stimulation by TNFα, the medium of the cells was exchanged to TNFα-deficient medium, and following additional 36 hr of cell growth, CM that were enriched in tumor-promoting factors such as CXCL8 (data not shown) were collected and injected to tumors." (PMID 24598028, 2014). "We speculate that NLRX1 expression will reflect the relative exposure to intrinsic apoptosis signals (such as nutrient availability) versus extrinsic apoptosis signals (such as inflammation-derived factors, including TNF) in normal tissue or the tumor microenvironment." (PMID 24867956, 2014).
tumor (continued). "Previously we showed that the profound hyporesponsiveness of Tregs to TCR stimulation in vitro could be overcome by exogenous TNF, a major proinflammatory mediator elevated in the tumor microenvironment with the capacity to promote growth and metastatic spread of cancer." (PMID 24416401, 2014). "It has been reported that a high peripheral neutrophil level, which was induced by inflammation-related cytokines (ie, interleukin-6 and tumor necrosis factor) or tumor-derived myeloid growth factors, may indicate systemic inflammation response or a tumor progression." (PMID 24718309, 2014). "In addition, TNF-α is not only produced by a wide variety of tumor cells but also by adipocytes." (PMID 24829560, 2014). "In addition, significant increases of tumor mass TNF-α, a representative cytokine involved in tumor necrosis immunoreactivities were also demonstrated in all three different dosages of platycodin D as compared with tumor-bearing control mice, respectively." (PMID 25477992, 2014). "The inflammatory components in a developing neoplasm may include several types of immune cells, including mast cells and neutrophils, which can produce an array of cytokines, such as the cell-killing mediators TNF-α and interleukins (ILs)." (PMID 25490767, 2014). "More importantly, by a serial transplantation of SE-tumor cells using sphere-forming assays, we found that the tumor-founding cells maintain these TNF-induced properties for generations after first exposure and that this activity may be mediated by the PI3K/AKT signaling pathway." (PMID 25223735, 2014). "TNF-α and IL-1β are the most potent pro-inflammatory cytokines produced by TAMs which, depending on their concentration, may either induce the expression of several genes resulting in the promotion of tumor cell aggression, or exert a cytotoxic effect." (PMID 25120672, 2014). "Thus, the powerful ability of hyper-activated Ras + TNFα to promote metastasis strongly suggests that TNFα activation of WT-Ras may lead to the dissemination of tumor cells." (PMID 24598028, 2014). "Nevertheless, this toxicity was not further enhanced by the addition of TRAIL/zVAD or TNF/zVAD, validating our assay conditions and indicating that the observed susceptibility/resistance of the employed tumor cell lines to programmed necrosis is not a matter of insufficient sensitization." (PMID 24507727, 2014). "Gelatinase B/MMP-9 activates pro-inflammatory cytokines TNFα and IL-1β, increases the activity of chemokines CXCL1, CXCL4, CXCL7 and CXCL8, releases TGFβ from matrix stores, is released by activated neutrophils in TIMP-1-free form and acts as a nanomolar effector of tumour associated inflammation." (PMID 24473089, 2014). "Moreover, the patient-derived tumor cells demonstrated IZ-induced autocrine expression of TNFα." (PMID 25356865, 2014). "The generation of an abundant tumor necrotic material, together with the known effect of TNFα in recruiting DC in inflammatory sites could be a crucial element to generate AAA for fueling professional APC, thus reaching optimal saturation of MHC class II molecule-tumor peptide complexes on DC." (PMID 24600588, 2014). "However, TAMs from several tumor models also exhibit typical M1 cytokines such as TNF-α and IL-1β." (PMID 25071759, 2014). "However, there are few reports on the function of tumor-derived TNF-α." (PMID 24676340, 2014). "Moreover, the miR-150-3p levels may be negatively correlated with plasma TNF-α level in patients and those miR-671-5p levels may regulate gene expression to promote tumour growth." (PMID 25231540, 2014). "In addition, TNF changes the function of immune cells, promoting tumor progression." (PMID 24676340, 2014). "Thus, fluvastatin may be used in tumor treatment sparing in NK cells the activating receptor-mediated release of antitumor soluble factors as FasL and TNFα and ADCC activity." (PMID 23667543, 2013).